AKR1C6P (aldo-keto reductase family 1 member C6, pseudogene)
Synonyms: TAKR
Gene: Transcribed unprocessed pseudogene on chromosome 10 (4,871,901 to 4,891,975, reverse strand). Ensembl gene ENSG00000151631.
Diseases named in the same sentence as AKR1C6P in open-access papers:
AKR1C6P is named in the same sentence as 1 disease in open-access papers, as found by Europe PMC text mining. Sharing a sentence is not in itself a finding about the gene and the disease.
AKR1C6P shares sentences with these, for which no sentence is quoted: tumor (1 paper).